CCR1 (C-C motif chemokine receptor 1)
Diseases named in the same sentence as CCR1 in open-access papers (continued):
Sharing a sentence is not in itself a finding about the gene and the disease.
colorectal cancer (23 papers, 2011 to 2025). A primary or metastatic malignant neoplasm that affects the colon or rectum. "Mechanistically, TRIM47 promotes the ubiquitination and degration of SMAD4 by interacting with SMAD4, and further increases the levels of C-C motif chemokine ligand 15 (CCL15) and C-C motif chemokine receptor 1 (CCR1), ultimately causing poor outcome of colorectal cancer." (PMID 30979374, 2019). "Recently, blockade of CCR1 by a neutralizing anti-CCR1 mAb in myeloid cells showed the therapeutic efficacy in a mouse model of colorectal cancer." (PMID 41542175, 2025). "Previous studies have shown that CCL15 can recruit CCR1+ bone marrow-derived inhibitory cells and CCR1+ neutrophils to promote liver metastasis of colorectal cancers 37-39." (PMID 35673582, 2022). "The knockdown of CCL15 in colorectal cancer cells was shown to diminish CCR1+ accumulation, and tumor growth was suppressed." (PMID 32443699, 2020). "Accumulating loss of SMAD4 leads to up-regulation of CCL15 and CCR1 expression, followed by higher activity and expression of MMP-9, ultimately causing colorectal cancer malignance." (PMID 30979374, 2019). "The chemokines C-C chemokine receptor type 1 (CCR1) and C-C motif receptor-like 2 (CCRL2) are associated with colorectal cancer liver metastasis: The expression modulation of CCR1 and chemokine CCRL2 were investigated in the same rat liver metastasis model." (PMID 28770169, 2017). "Accumulation of CCR1+TANs was reported in lung metastasis of colorectal cancer CCL15-CCR1 axis." (PMID 40352924, 2025). "Mast cells interacted with Immunology2 through Ccl5⇔Ccr1, a specific pathway that recruits monocytes into inflamed tissues by primarily triggering Ccr1-mediated arrest on endothelial cells, and has been shown to promote hematogenous metastasis in colorectal cancer." (PMID 39026350, 2024). "According to reports, the CCR1/CCR5 axis is involved in the liver metastasis of colorectal cancer." (PMID 39030403, 2024). "Furthermore, the same group showed that colorectal cancer cells with the loss of the tumor suppressor SMAD4 secreted CCL15 and recruited CCR1+ myeloid cells to assist tumor invasion in colorectal cancer patients." (PMID 35267547, 2022). "High levels of CCRL2 and CCR1 were also found in liver metastases of colorectal carcinoma in rats, but the consequences of CCRL2 expression appeared limited in human primary colorectal carcinoma cells in terms of proliferation, clonogenic capacity, migration, and survival." (PMID 34638484, 2021). "Accordingly, high levels of CCR1 in patients with multiple myeloma have been linked to decreased overall survival, and increased levels of SLAMF8 mRNA have been identified as a prognosticator of worse survival in patients with high-grade gliomas and colorectal cancer." (PMID 37509358, 2023). "Recently, there have been multiple publications which indicate CCR1 as a mediator of TAM induced metastasis in several cancer models including breast and colorectal cancer." (PMID 36982211, 2023). "There are also several recent studies in the literature which highlight the role of CCR1 in mediating TAM recruitment and colorectal carcinoma (CRC) metastasis to the lung and liver." (PMID 36982211, 2023). "Most of the CCR1+ cells were G-MDSCs, and the CCL15 levels in the sera of colorectal cancer patients were significantly higher than those in controls." (PMID 32443699, 2020). "Reference 40 to “Akram, I.G.; Georges, R.; Hielscher, T.; Adwan, H.; Berger, M.R. The chemokines CCR1 and CCRL2 have a role in colorectal cancer liver metastasis." (PMID 31146450, 2019). "Akram, I.G.; Georges, R.; Hielscher, T.; Adwan, H.; Berger, M.R. The chemokines CCR1 and CCRL2 have a role in colorectal cancer liver metastasis." (PMID 31146450, 2019).
colorectal cancer (continued). "SMAD4 deletion promotes colorectal cancer (CRC) expression of C-C Motif Chemokine Ligand 15 (CCL15) and recruits the CCR1 TAN (CCL15-CCR1 axis) with arginase-1 (ARG-1) and matrix metalloproteinase 9 (MMP-9) activities, thereby forming a pre-metastatic niche for disseminated tumor cells (e." (PMID 40160822, 2025). "Similarly, in colorectal cancer, THRC1-induced upregulation of CCL15 facilitates the recruitment of CCR1+ macrophages, thereby enhancing tumor progression." (PMID 40740234, 2025). "Dual blockade of CCR1 and CXCR2 pathways in myeloid cells could be an effective therapy against colorectal cancer." (PMID 38750114, 2024). "In previous studies, CCR1 blockade with the antagonist CCX721 reduced tumour burden and osteolysis in a mouse model of myeloma bone disease, while another CCR1 antagonist, BL5923, was able to suppress liver metastasis from colorectal cancer." (PMID 36241867, 2022). "In addition, CCR1 knockdown significantly limits the activity and expression of matrix metalloproteinase-2 (MMP-2) and MMP-9, which predicts poor survival in colorectal cancer." (PMID 30979374, 2019). "Furthermore, CCR1+ and CXCR2+ myeloid cells were concentrated around the tumor invasion front in our mouse model, which is consistent with a previous human CRC study and data from a public database from human colorectal cancers." (PMID 38750114, 2024).
hepatocellular carcinoma (23 papers, 2014 to 2025). A malignant tumor that arises from hepatocytes. "CCR1 has recently been implicated in tumor invasion and metastasis in various cancers, such as prostate cancer, colon cancer, and hepatocellular carcinoma." (PMID 37444610, 2023). "CCR1 can activate the AKT-ESR1 to promote hepatocellular carcinoma cell proliferation and migration 46 and enhances prostate cancer cell invasive via activating ERK1/2 and Rac signaling." (PMID 40740234, 2025). "CCL5 activity is mediated through its binding to CCR5, CCR3, and CCR1 but only CCR1 is expressed in hepatocellular carcinoma cells (HCC)." (PMID 35399952, 2022). "In particular, CCR1 has been shown to be involved in metastasis for numerous cancers including ovarian, breast, prostate, hepatocellular carcinoma, oral squamous cell carcinoma, non-small cell lung, and multiple myeloma." (PMID 35399952, 2022). "CCR1 mRNA and protein are widely expressed in hepatoma cell lines, and CCL3 and CCR1 are essential to the growth and progression of HCC." (PMID 27221035, 2016). "In our study, we sought to construct a novel RNAi vector simultaneously expressing VEGFR2, CCR1, and EpCAM shRNA cassettes and test its effects on hepatoma cell lines." (PMID 27221035, 2016). "For instance, in hepatocellular carcinoma, CCL15 recruits CCR1+ monocytes to support immune evasion and metastasis." (PMID 40740234, 2025). "In human hepatocellular carcinoma, most abundantly expressed CCL15 recruited CCR1+ CD14+ monocytes toward HCC invasive margin to enhance tumor metastasis by inducing immune suppression and angiogenesis." (PMID 35267547, 2022). "These include evaluation of the CXCL12/CXCR4 axis in angiogenesis, the CCL20/CCR6 axis in the growth of the hepatoma cell line Huh7; and the CCL5/CCR1 axis in promoting the metastasis and invasion of HCC cells." (PMID 32260550, 2020). "Likewise, human hepatocellular carcinoma (HCC) cells express CCR1 and its ligands can affect the functions of human HCC cell lines." (PMID 24966464, 2014). "In hepatocellular carcinoma (HCC), tumor infiltrating DCs express the chemokine GPCRs, CCR1 and CCR5." (PMID 25110692, 2014). "Moreover, contrasting CCL7’s predominant activation of TGF-β-induced EMT in hepatocellular carcinoma, CAF-derived CCL7 in OSCC primarily operated through CCR1 activation and downstream signaling." (PMID 41430036, 2025). "Three specific receptors of CCL5 include CCR1, CCR3, and CCR5.We also found that CAF-derived CCL5 or exogenous hCCL5 could obviously enhanced the expression of CCR3 and CCR5 in hepatocellular carcinoma cells." (PMID 35589690, 2022). "CCL23 has been found to be underexpressed in hepatoma cells, and this could lead to CCL23 deletion and reduced CCL23 inhibition via the ESR1/CCL23/CCR1/AKT regulatory axis in liver cancer progression." (PMID 36425563, 2022). "CCR1, the main and specific receptor for CCL15, is a G protein-coupledreceptor that is expressed by a variety of cells such as monocytes, lymphocytes, neutrophils, eosinophils and hepatocellular carcinoma cells." (PMID 30979374, 2019). "Furthermore, in cases of hepatocellular carcinoma (HCC), tumor cells harness the CCL4/CCL5 chemokine pathway, interacting with the CCR1/CCR5 receptors, thereby orchestrating the mobilization of γδ T cells either from the peripheral blood or peritumor region to the tumor region." (PMID 38077392, 2023). "On the other hand, a study demonstrated that the absence of CCL3/CCR1, but not CCL3/CCR5, resulted in a decreased incidence of hepatocellular carcinoma." (PMID 28881626, 2017).
colon cancer (21 papers, 2010 to 2025). "Other groups also reported that in addition to myeloid cells, these colon cancer cells were also able to recruit CCR1+ tumor-associated neutrophils to facilitate lung metastasis through the expression of CCL15." (PMID 38731942, 2024). "We demonstrated recently that CCR1 plays critical roles in liver metastasis of Smad4-deficient colon cancer in a mouse model." (PMID 25326065, 2014). "The recruitment of CCR1+ neutrophils in early phase of colon cancer dissemination appears to cause that of fibrocytes in late phase." (PMID 25326065, 2014). "To dissect the contribution of the CCR1- and CCR2-signaling pathways to monocyte/macrophage recruitment, we used lung and colon tumor models in Ccr1- and Ccr2-deficient mice in combination with adoptive transfer of monocytic cells during the early phase of metastasis." (PMID 39566333, 2025). "Ccr1 expression was also shown to be essential for the recruitment of immature myeloid cells during liver metastasis in a colon cancer model." (PMID 39566333, 2025). "We initially measured the mRNA expression levels of ligands for CXCR2 and CCR1 in mouse colon cancer cell lines (MC38, CMT93, CT26 and Colon-26) and a normal rat intestinal cell line (IEC-6)." (PMID 38750114, 2024). "Targeted CCR1 downregulation was able to halt the metastatic expansion of colon cancer cells to the liver in vivo through the blockade of immature myeloid cell recruitment." (PMID 37509358, 2023). "Reference 41 to “Hirai, H.; Fujishita, T.; Kurimoto, K.; Miyachi, H.; Kitano, S.; Inamoto, S.; Itatani, Y.; Saitou, M.; Maekawa, T.; Taketo, M.M. CCR1-mediated accumulation of myeloid cells in the liver microenvironment promoting mouse colon cancer metastasis." (PMID 31146450, 2019). "Hirai, H.; Fujishita, T.; Kurimoto, K.; Miyachi, H.; Kitano, S.; Inamoto, S.; Itatani, Y.; Saitou, M.; Maekawa, T.; Taketo, M.M. CCR1-mediated accumulation of myeloid cells in the liver microenvironment promoting mouse colon cancer metastasis." (PMID 31146450, 2019). "Namely, CCR1 was shown to mediate the accumulation of myeloid cells in the liver microenvironment, enhancing mouse colon cancer metastasis, and additionally, to affect liver metastasis and angiogenesis in a thymoma model." (PMID 30764543, 2019). "For example, a CCR1 antagonist (BL5923) can suppress metastatic tumor growth of colon cancer cells in the liver, and another CCR1 antagonist (CCX721) reduces tumor burden and osteolysis in a mouse model of multiple myeloma bone disease." (PMID 30483271, 2018). "TNF-α-primed-hMSCs secrete high level of CCL5, which interacts with its receptor CCR1 expressed in colon cancer cells." (PMID 28542126, 2017). "Collectively, these results indicate that CCL5/CCR1 axis plays an important role in preactivated-hMSC-mediated colon cancer progression." (PMID 28542126, 2017). "Collectively, these results suggest that CCL5/CCR1/β-catenin/Slug pathway is responsible for the tumor-promoting effects of TNF-α-activated hMSCs on the development of colon cancer." (PMID 28542126, 2017). "Taken together, CCL5/CCR1 axis appears to be crucial in mediating a crosstalk between MSCs and cancer cells to induce colon cancer cell EMT and metastasis." (PMID 28542126, 2017). "So far no clinical trials are underway for CCR1 antagonists in a cancer setting, however, a preclinical study indicates that CCR1 antagonist (BL5923) can suppress metastatic tumor growth of colon cancer cells in the liver." (PMID 26275794, 2015). "We suggested that CCR1+ bone marrow (BM)-derived cells are recruited to the microenvironment of disseminated colon cancer cells, and produce metalloproteinases MMP9 and MMP2, helping metastatic colonization." (PMID 25326065, 2014). "To further determine which receptor on colon cancer cells is responsible for the paracrine effect of CCL5 secreted by hMSCs, we examined the mRNA expression levels of ccr1, ccr3, and ccr5 in SW1116." (PMID 28542126, 2017).
colon cancer (continued). "In the liver metastatic lesions of human colon cancer, on the other hand, only a small fraction (~10 %) of CD14+ monocytes expressed CCR1 by immunohistochemistry, whereas most of the CD15+ myeloid cells with mononuclear morphology expressed CCR1." (PMID 25326065, 2014). "Similarly, in colon cancer, cancers that lack SMAD4 expressed more CCL15, which attracted CCR1+ myeloid cells, leading to enhanced liver metastasis." (PMID 38731942, 2024). "While CCL5 can bind to CCR1, CCR3, and CCR5, we revealed that the paracrine CCL5-induced cell migration in colon cancer cells was mainly mediated by CCR1, given that CCR1 antagonist completely abolished the increased migration in colon cancer cells in response to CCL5." (PMID 28542126, 2017). "Similarly, the CCR1 inhibitor BX-471 and the CCR1 antagonist BL5923 were able to decrease myeloma growth and inhibit colon cancer liver metastasis respectively." (PMID 26062132, 2015). "Additionally, studies have reported that inhibiting CCR1 with the receptor antagonist BL5923 suppresses the recruitment of immature myeloid cells, leading to a reduction in metastatic colon cancer and a significant prolongation of survival in mice with colon cancer liver metastasis." (PMID 38274805, 2023).
Arthritis (19 papers, 2011 to 2026). Inflammation of a joint. "The upregulation of chemokine receptors Ccr1, Ccr2, and Ccr5 are associated with macrophage and endothelial cell infiltration in arthritis." (PMID 29197380, 2017). "Mice deficient in CCR1 displayed a significant reduction in joint inflammation and the severity of disease as shown by the arthritis score." (PMID 25170619, 2014). "In CAIA, the arthritis score of mice treated with BI33 at 30 mg/kg was also significantly reduced to a level comparable with CCR1-deficient mice." (PMID 25170619, 2014). "In a mouse model of arthritis, CCR1 increased neutrophil crawling on the endothelium, while CXCR2 increased neutrophil retention and survival within the joints." (PMID 38750114, 2024). "It is noteworthy that the CCR1 antagonist dose utilized in the study has been reported to be effective against experimental arthritis." (PMID 34203121, 2021). "B cells from the SF of arthritis patients showed a significant increase in the surface expression of CCR1, CCR2, CCR4, CCR5 and CXCR4 with respect to PB." (PMID 29880013, 2018). "Nevertheless, we also demonstrate that a specific CCR1 antagonist reduces arthritis in the pre-clinical CAIA mouse model." (PMID 25170619, 2014). "In this regard, a sequential role for the leukotriene B4 receptor Blt1, Ccr1 and Cxcr2 has previously been reported for neutrophil recruitment in a mouse model of arthritis." (PMID 22916017, 2012). "Nevertheless, these data suggest that the local induction of CXCR2 and CCR1 chemokines in the synovium is likely the major mechanism of the amplification of serum-induced arthritis by IL-17RA signaling." (PMID 22028860, 2011). "CCR1 may also play a role in macrophage and endothelial cell infiltration in experimental arthritis models partly through activating JAK signaling." (PMID 37384596, 2023). "OCPs from patients with arthritis had higher expression of CCR1, CCR2, CCR4, CXCR3, and CXCR4." (PMID 28619088, 2017). "Indeed, in a model of arthritis, CCR1 blockade or depletion enhanced systemic TNF production." (PMID 29696014, 2018). "Especially, CCR1, CCR2 and CCR5 are abundantly expressed on RA synovial macrophages and the validity of CCR1, CCR2 and CCR5 antagonist for the animal model of arthritis has been studied." (PMID 25248373, 2014). "During autoantibody-induced arthritis, the recruitment of neutrophils in the inflamed joint requires a cascade of cytokines and chemokines (LTB4, IL-1β, CCR1, and CXCR2 ligands) produced by endothelial cells, synovial cells, and neutrophils themselves." (PMID 24968718, 2014). "We have recently shown that CCR1 and CXCR2 are needed for the development of full-blown serum-induced arthritis." (PMID 22028860, 2011). "Additionally, other studies have shown that the expression of CCR1, CCR2, CCR4, CCR5, and CXCR4 on the surface of B cells in synovial fluid (SF) of arthritis patients is significantly increased." (PMID 41481752, 2026). "Double-knockout mice for CCR1 and CXCR2 have been studied for research on arthritis." (PMID 38750114, 2024). "It was reported that deficiency of CCR9, as well as CCR1, CCR2 and CCR5, did not attenuate a murine model of serum transfer arthritis." (PMID 25248373, 2014). "Utilizing several strains of chemokine receptor-knockout mice, these authors found that CXCR2, not CCR1, was important in their pre-clinical arthritis mouse model." (PMID 25170619, 2014). "We have recently shown that CCR1 and CXCR2 play crucial non-redundant roles in serum-induced arthritis and together account for all of the neutrophil chemokine activity in the model." (PMID 22028860, 2011).